GCG (glucagon)
Diseases named in the same sentence as GCG in open-access papers (continued):
Sharing a sentence is not in itself a finding about the gene and the disease.
Sepsis (19 papers, 2013 to 2025). Sepsis is defined as life-threatening organ dysfunction caused by a dysregulated host response to infection. "In the present study, we assessed the contribution of glucagon on the increased susceptibility of diabetic mice to sepsis induced by CLP, focusing on the effects of glucagon on neutrophil migration." (PMID 34295325, 2021). "Altogether, our results suggest that glucagon may be involved in the reduction of neutrophil migration and increased susceptibility to sepsis in diabetic mice." (PMID 34295325, 2021). "Furthermore, in patients with sepsis, increased glucagon levels caused by a decreased endogenous secretion of intestinal glucagon have been associated with disease severity and poor prognosis (Jung and Park." (PMID 34335269, 2021). "Sepsis leads to a surge in stress hormones in the blood, including catecholamines, cortisol, growth hormone, and glucagon." (PMID 39838305, 2025). "Second, there is an increase in stress hormones, including cortisol, growth hormone, glucagon, and catecholamines, during sepsis, which themselves have lipolytic properties." (PMID 39838305, 2025). "They followed 112 sepsis patients through their hospital stay and measured their glucagon levels at days 0, 1, 3, and 7, correlating them with the clinical picture." (PMID 39838305, 2025). "This is because critical illnesses such as trauma, sepsis, and burns activate the sympathetic autonomic nervous system, which stimulates in the production of hormones such as epinephrine and glucagon." (PMID 37118670, 2023). "A similar approach was used to identify sepsis-induced decreases in the activation of G-protein coupled receptors by catecholamines, growth hormone and glucagon, and in assessing the abundance of the α isoform of the glucocorticoid receptor." (PMID 37550630, 2023). "Insulin levels were in the low normal range upon presentation (opposite to glucagon) and the levels were normalized upon resolution of sepsis." (PMID 34659208, 2021). "Sepsis is considered an acute stress response with a release of stress hormones including cortisol and glucagon." (PMID 34659208, 2021). "According to recent studies, peptide hormones of mammals like ghrelin, hCG, glucagon, glucagon-like peptide 1, and vasopressin have shown promising effects on sepsis, presumably based on their anti-inflammatory properties." (PMID 33584688, 2020). "Moreover, our results revealed that the mechanism of SFH for treating sepsis is related to the improvement of gut microbiota dysbiosis and modulation of the Glucagon signaling pathway, PPAR signaling pathway, Galactose metabolism, and Pyrimidine metabolism." (PMID 36970673, 2023). "The mechanism of SFH for treating sepsis may be ascribed to the enrichment of beneficial gut flora and modulation in glucagon signaling pathway, PPAR signaling pathway, galactose metabolism, and pyrimidine metabolism." (PMID 36970673, 2023). "In addition, the severity of sepsis has a close relationship with increased circulating levels of glucagon." (PMID 34295325, 2021). "Thus, inflammation/CLP/sepsis-induced increases in endogenous levels of epinephrine, glucagon, cortisol, and pro-inflammatory cytokines and treatments such as norepinephrine administration may limit the ability to assess the effects of insulin." (PMID 37550630, 2023). "In addition, serum insulin could possibly be elevated in babies with sepsis in reaction to the effect of stress and other counter-regulatory hormones like glucagon and cortisol." (PMID 32637004, 2020). "In animal models of sepsis, intestinal glucose can induce the decrease of intestinal glucose levels and blood sugar, and GIP promotes insulin secretion, reduces glucagon secretion, increases insulin secretion, weakens the systemic inflammatory response, and improves hemodynamics." (PMID 34335269, 2021).
Sepsis (continued). "Since glucagon presents anti-inflammatory and immunomodulatory effects on neutrophils, this work aimed to evaluate the role of glucagon on the impaired neutrophil migration observed in diabetic animals submitted to cecum ligation and puncture (CLP)-induced sepsis." (PMID 34295325, 2021). "Moreover, lipolysis is also upregulated, causing increased blood concentrations of free fatty acids and triglycerides under the release of stress hormones such as (nor)epinephrine and glucagon during sepsis." (PMID 35911117, 2022).
diabetic ketoacidosis (18 papers, 2013 to 2025). The metabolic condition resulted from uncontrolled diabetes mellitus, in which the shift of acid-base status of the body toward the acid side because of loss of base or retention of acids other than carbonic acid is accompanied by the accumulation of ketone bodies in body tissues and fluids. "Euglycemic diabetic ketoacidosis is primarily caused by changes in insulin/glucagon ratio, increased ketogenesis, glycosuria, and the ketone reabsorption effect of SGLT2i." (PMID 40429346, 2025). "Due to the relationship between glucagon and ketone bodies, critically ill patients can present with a significantly higher risk of developing diabetic ketoacidosis." (PMID 36819350, 2023). "It has been hypothesized that this switch from carbohydrate to lipid utilization among others, such as reduced ketone clearance and stimulation of glucagon secretion, might explain the elevated risk of diabetic ketoacidosis under therapy with SGLT2 inhibitors." (PMID 30922297, 2019). "Moreover, glucagon is implicated in the pathogenesis of diabetic ketoacidosis." (PMID 31365624, 2019). "It is important to note that the pathophysiology of diabetic ketoacidosis is well known and is characterized by a relative or absolute lack of insulin and by an excess of counterregulatory hormones such as corticosteroids, glucagon, and catecholamines." (PMID 38899266, 2024). "Diabetic ketoacidosis usually occurs due to absolute or relative insulin lack accompanied by increased glucagon, cortisol, growth hormone, and epinephrine." (PMID 37363479, 2023). "Supplementation of insulin can inhibit lipolysis and ketone production, as well as decrease glucagon secretion, and is thus the main treatment for diabetic ketoacidosis." (PMID 29258472, 2017). "As fructose acutely increased glucagon levels in T1DM patients, it is possible that the chronic use of this sugar as a sweetener might increase the risk of diabetes ketoacidosis in these individuals." (PMID 31365624, 2019). "Two episodes of diabetic ketoacidosis with a positive GAD65-Ab test in 2017 and marginal residual beta-cell function detected upon glucagon stimulation test confirmed the diagnosis of LADA." (PMID 32982980, 2020).
Cirrhosis (16 papers, 2012 to 2025). A chronic disorder of the liver in which liver tissue becomes scarred and is partially replaced by regenerative nodules and fibrotic tissue resulting in loss of liver function. "The screened GYS1, PYGL and PHKG1 genes play crucial roles in the glycogenolysis step of the glucagon signaling pathway, and their overexpression destabilizes glycogenolysis and predisposes one to glycogen storage disease, which can lead to cirrhosis and liver fibrosis." (PMID 36430769, 2022). "In healthy volunteers, the transient glycaemia observed following glucagon injection is due to increased glycogenolysis; this increase in glycogenolysis is attenuated in patients with cirrhosis, even when they are glycogen replete." (PMID 38579751, 2024). "Hospitals where carvedilol is used in patients with cirrhosis should have glucagon in formulary at doses to treat toxicity (bolus and infusion)." (PMID 29214053, 2017). "Some animal studies have shown that octreotide decreases the level of glucagon, eventually improving the vasoconstrictors effect of norepinephrine in patients with cirrhosis." (PMID 24282425, 2013). "Patients with NAFLD and cirrhosis had hyperglucagonemia as a potential sign of glucagon resistance." (PMID 37078380, 2023). "Also, individuals with hepatic cirrhosis presented with hyperglucagonemia, hyperaminoacidemia, and impaired ureagenesis in response to glucagon." (PMID 36686477, 2022). "The iAUC for postprandial glucagon concentrations was significantly higher in NAFLD compared to healthy (p = 0.026) and cirrhosis (p = 0.037)." (PMID 37078380, 2023). "Fasting hyperglucagonemia was present in cirrhosis and both oral (50g glucose OGTT) and i.v. glucose suppressed plasma glucagon." (PMID 36686477, 2022). "However, abnormal glucagon levels alone may not fully explain the skin findings, as elevated glucagon is also observed in conditions such as trauma, burns, diabetic ketoacidosis, starvation, and cirrhosis, none of which are typically associated with the characteristic rash." (PMID 41403981, 2025). "We found increased concentrations of glucagon in both NAFLD and cirrhosis patients." (PMID 37078380, 2023). "The glucagon insulin ratio was decreased in NAFLD and cirrhosis compared to healthy." (PMID 37078380, 2023). "However, urea synthesis becomes unresponsive to glucagon in cirrhosis, a phenomenon that would also be expected to occur in NAFLD, with its high glucagon levels." (PMID 37425212, 2023). "In a previous study, our colleagues examined 20 patients with and 21 patients without cirrhosis; they compared them with delta C‐peptide immunoreactivity using the glucagon challenge test and pancreatic perfusion parameters through dynamic contrast‐enhanced ultrasound." (PMID 35437902, 2022). "On the other hand, in patients with cirrhosis, lack of response to vasoconstrictors, such as norepinephrine, in the splanchnic area is due to the increased level of both endothelial (nitric oxide) and nonendothelial vasodilators (glucagon)." (PMID 24282425, 2013).
diabetic kidney disease (16 papers, 2015 to 2025). Progressive kidney disorder caused by vascular damage to the glomerular capillaries, in patients with diabetes mellitus. "Of particular note, previous studies have indicated that increased glucagon levels are associated with an elevated risk of diabetic kidney disease." (PMID 41458542, 2025). "One cross-sectional study indicated that, after adjusting for covariates including demographic characteristics, lipid-lowering drugs, and hypoglycemic agents, increased glucagon levels were independently associated with an increased risk of diabetic kidney disease." (PMID 41458542, 2025). "Here, we investigated whether long-term increased plasma levels of glucagon contribute to the pathophysiological changes seen in diabetic nephropathy, using mouse models of long-term activation and inactivation of glucagon receptor signaling." (PMID 39265079, 2024). "We investigated whether long-term increased plasma levels of glucagon contribute to the development of pathophysiological changes in kidney function as seen in patients with diabetic nephropathy." (PMID 39265079, 2024).
hyperlipidemia (16 papers, 2012 to 2025). "Hyperlipidaemia-induced AP can promote the release and activation of lipase, catecholamine, glucagon, and growth hormones, thereby accelerating the metabolism of fats within organs and tissues, leading to their release into the bloodstream." (PMID 38578756, 2024). "Additionally, palmitate can stimulate secretion of glucagon in isolated human islets via free fatty acid receptor at fasting glucose levels, and postprandial lipemia increased plasma glucagon concentrations in humans." (PMID 34174950, 2021). "The glucagon to insulin ratio was a significant predictor even after adjusting for HbA1c, LDL-C, and use of hyperlipidemia medications, and the same was true after additionally adjusting for incretins (iGLP-1, iGIP), hsCRP (cardiovascular risk factor), fibrinogen, and uric acid." (PMID 37762748, 2023).
metabolic dysfunction-associated steatohepatitis (16 papers, 2016 to 2026). Metabolic dysfunction-associated steatohepatitis (MASH, formerly known as nonalcoholic steatohepatitis or NASH) is a type of fatty liver disease. "Studies in individuals with NAFLD and non-alcoholic steatohepatitis (NASH) illustrate that fat accumulation in the liver reduces the sensitivity of hepatocytes towards glucagon." (PMID 33275161, 2021). "Survodutide: A dual agonist of glucagon and GLP-1 receptors, survodutide has shown potential benefits in metabolic dysfunction-associated steatohepatitis (MASH), including improving fatty acid oxidation, reducing lipogenesis, and suppressing hepatic inflammation." (PMID 40282969, 2025).
colon carcinoma (15 papers, 2005 to 2025). "Colorectal cancer is highly prevalent and causes high global mortality, and glucagon axis has been implicated in colon cancer." (PMID 35340411, 2022). "In human colon cancer cell lines, GCG activates its receptor, which leads to cancer cell proliferation by affecting AMPK/MAPK signaling." (PMID 35340411, 2022). "In contrast, some previous work has shown that hyperglucagonemia promotes colon cancer in vivo, noting increased GCG receptor expression in colon cancer tissue, and in vitro GCG stimulation led to COADREAD cell proliferation." (PMID 35340411, 2022). "To ascertain the functionality of glucagon in mouse colon cancer cell lines, we measured changes in intracellular cAMP concentrations before and after glucagon stimulation." (PMID 29535833, 2018). "In this study, the direct effect of glucagon on colon cancer was investigated, and the glucagon mechanism of action as an activator of colon cancer cell proliferation in vitro was elucidated." (PMID 29535833, 2018). "Taken together, these results showed that glucagon enhances colon cancer cell growth through regulation of proliferative signaling including the AMPK and MAPK pathways." (PMID 29535833, 2018). "The effect of glucagon on GCGR-mediated signaling pathways was investigated using mouse colon cancer cell lines CMT93 and CT26." (PMID 29535833, 2018). "In the present study, the in vitro experiments showed a modest effect of glucagon on colon cancer cell proliferation compared to in vivo studies." (PMID 29535833, 2018). "In the present study, glucagon suppressed the phosphorylation of AMPK at Thr172 in colon cancer cells through activation of the GCGR pathway." (PMID 29535833, 2018). "Also, glucagon signaling is shown to significantly stimulate proliferation in colon cancer cell lines." (PMID 32511227, 2020). "Next, AMPK signaling regulated by glucagon in colon cancer cells was investigated." (PMID 29535833, 2018). "Although a previous study demonstrated the stimulating effect of glucagon on the growth of human colorectal adenocarcinoma cells obtained from patients in vitro, the mechanism of how glucagon stimulates colon cancer cell proliferation remains unclear." (PMID 29535833, 2018). "Additionally, GCGR-mediated signals involving colon cancer cell growth were investigated to elucidate the mechanism of how glucagon regulates cancer cell growth." (PMID 29535833, 2018). "Moreover, glucagon was demonstrated to promote colon cancer cell proliferation through binding to GCGR expressed in human and mouse colon cancer cell lines." (PMID 29535833, 2018). "A similar scenario might apply to colon glucagon gene expression, as this growth stimulatory peptide for colon cancer cells was inhibited by WPH at the level of colon mRNA abundance." (PMID 15644144, 2005). "The effect of the activator of AMPK, AICAR, or the specific inhibitor of MAPK, PD98059, on cell proliferation of CMT93 stimulated by glucagon was examined to investigate whether these factors are involved in glucagon-mediated promotion of colon cancer cell growth." (PMID 29535833, 2018). "Although further studies are needed to identify the detailed mechanisms of how glucagon regulates AMPK, we believe that glucagon induces inhibitory activity against AMPK and consequently enhances cell growth in colon cancer cells." (PMID 29535833, 2018). "Furthermore, to identify the mechanisms promoting colon cancer cell growth by glucagon, the activation of downstream signals of GCGR was examined by western blotting using colon cancer cells treated with glucagon." (PMID 29535833, 2018). "Glucagon significantly promoted colon cancer cell growth, and GCGR knockdown with small interfering RNA attenuated the proliferation-promoting effect of glucagon on colon cancer cells." (PMID 29535833, 2018). "However, the mechanism of how glucagon promotes colon cancer cell proliferation has not yet been determined." (PMID 29535833, 2018).
colon carcinoma (continued). "In the current study, glucagon was found to increase phosphorylation of ERK1/2 in colon cancer cells, and glucagon did not phosphorylate ERK1/2 in GCGR knockdown colon cancer cells, resulting in attenuation of the promoting effect of glucagon on cell growth." (PMID 29535833, 2018). "Besides that, glucagon was found to enhance colon cancer cell proliferation, whereas glucagon did not promote cell proliferation in GCGR knockdown colon cancer cells." (PMID 29535833, 2018). "To determine whether glucagon is functional in GCGR expressing colon cancer cell lines, we measured intracellular cAMP concentrations in HT29 and SW480 with or without glucagon stimulation." (PMID 29535833, 2018).
polycystic ovary syndrome (15 papers, 2014 to 2025). A disorder that manifests as multiple cysts on the ovaries. "In another preclinical study, GE demonstrated superior metabolic effects compared to GLP-1-GIP or GLP-1-GIP-glucagon multiagonist therapies in models of polycystic ovary syndrome (PCOS), a condition frequently associated with obesity and insulin resistance." (PMID 40642529, 2025).